ERBB2 (erb-b2 receptor tyrosine kinase 2)
Diseases named in the same sentence as ERBB2 in open-access papers (continued):
Sharing a sentence is not in itself a finding about the gene and the disease.
breast cancer (continued). "In in vitro studies, sensitivity of breast cancer cells to the anti-human ErbB2 (HER2) monoclonal antibody, trastuzumab, was associated with the availability of HS on the cell surface and with the ability of HS to elicit the antibody response by forming a ternary complex with trastuzumab and HER2." (PMID 30413079, 2018). "Since its introduction in 1998, trastuzumab has dramatically improved the clinical history of breast cancer patients, but unfortunately it has been shown to cause cardiac dysfunction, since ErbB2 has been proven to be an important modulator of myocardial function." (PMID 29467663, 2018). "Therefore, our understanding of how ErbB2 cooperates with other oncogenic pathways in context of ErbB2 targeted therapies is critical for improvement of therapeutic outcomes in these high risk breast cancer patients." (PMID 27791982, 2017). "Breast cancers, including the erbB-2-overexpressing subtype, are often associated with morbidity and poor clinical outcomes; therefore, the identification and development of effective erbB-2-overexpressing breast cancer prevention and treatment options are crucial." (PMID 28193239, 2017). "Furthermore, ILC patients with tumors carrying both CDH1 and ERBB2 mutations have a worse prognosis, but represent an actionable group who may benefit from targeted breast cancer therapy." (PMID 27811364, 2016). "Some of these proteins have been reported to have potential clinical significance and key proteins, such as the receptor tyrosine-protein kinase erbB-2 (ERBB2) and breast cancer 1 and 2 early onset, may be used as potential diagnostic, prognostic or predictive biomarkers." (PMID 24932247, 2014). "Because MM-121 mainly inhibits activation of erbB3 and Akt in erbB2-overexpressing breast cancer cells, it is conceivable to hypothesize that MM-121 may abrogate erbB3 signaling-mediated therapeutic resistance to tamoxifen, trastuzumab, and other chemotherapeutic agents, such as doxorubicin." (PMID 24168763, 2013). "However, on the other hand, several works have demonstrated that the expression of FOXP3, especially in breast cancer cells, is an X-linked cancer suppressor gene and an important regulator of the epidermal growth factor receptor (HER2/ErbB2) and SKP2 oncogenes." (PMID 24350059, 2013). "Consequently, ERBB2 mRNA levels would be increased in breast tumors with these genetic variants, suggesting that genetic variants that influence hsa-miR-125a expression have potential as genetic markers of breast cancer." (PMID 23420759, 2013). "ErbB2 gene amplification in primary human breast cancer might increase the levels of this oncogenic variant above a critical threshold, therefore allowing it to contribute to breast cancer progression." (PMID 22007291, 2012). "In the present work, we attempted to analyze the cat ERBB2 gene SVs in the genomes of cat mammary lesions (which include benign and malignant lesions), determine frequent haplotypes and establish putative associations between SVs and mammary tumor clinicopathological features." (PMID 22489125, 2012). "The association of oncogene kinases (ErbB2, Src), a signaling transmembrane ligand (EphrinB1) and a phosphatase tumor suppressor (PTPN13) suggest that EphrinB1 may be a relevant therapeutic target in breast cancers harboring ErbB2-activating mutations and decreased PTPN13 expression." (PMID 22279592, 2012). "Indeed, radioresistance of breast cancer has been associated with erbB2 overexpression." (PMID 21876697, 2011). "The existence of IGF-IR/ErbB2 heterodimers has also been established and this association was shown to contribute to Herceptin resistance in human breast cancer cell lines; this interaction could be disrupted by treating with monoclonal antibody based therapy to IGF-IR." (PMID 20825649, 2010).
breast cancer (continued). "This amplicon encompasses many genes and it is conceivable that, as suggested by the variability of response to anti-ERBB2 therapy in patients with ERBB2 amplification, more than one gene in the amplicon could contribute to breast cancer susceptibility, development and progression." (PMID 17117180, 2006). "Similarly, ErbB2 is present in 10–40% of breast cancer cases and is associated with poor survival." (PMID 16519802, 2006). "Although the gene products of ATM, CHEK2 and ERBB2 are involved in various aspects of breast cancer development and progression, our results suggest that common variation in these genes does not affect survival, tumour-characteristic-defined risk or the overall risk of breast cancer." (PMID 17132159, 2006). "Amplification and overexpression of ERBB-2 in human breast cancer is thought to play a significant role in the progression of the disease; however, its precise role in the aetiology of altered phenotypes associated with human breast cancer is unknown." (PMID 10682681, 2000). "The identification of HER2 (also known as ERBB2) marked a major advance in breast cancer therapeutics." (PMID 41510186, 2026). "One such example is the amplification spanning the ERBB2 oncogene in the HCC1954 breast cancer genome." (PMID 41482535, 2026). "Despite the aggressive nature of ERBB2-positive breast cancers, the development of anti-ERBB2 therapy has resulted in better prognoses." (PMID 41955423, 2026). "MAGT1 mutations were not statistically significantly associated with overall survival (OS) in breast cancer, but MAGT1 mutations were closely associated with ERBB2 and CDH1." (PMID 42006149, 2026). "The CDK12 gene is located on chromosome 17q12, approximately 200 kb upstream of ERBB2 (HER2) oncogene, and is frequently co-amplified with HER2 in HER2+ breast cancers." (PMID 41491919, 2026). "The treatment responses seen in our study, in cancer types beyond FDA-approved ErB2-positive breast cancer, suggests that ErbB2 is emerging as a potential target across tumor types." (PMID 39908697, 2025). "In breast cancer, miR-155-5p was found to suppress the malignant transformation of breast epithelial cells by targeting ErbB2 expression." (PMID 39990676, 2025). "This updated analysis from the ShortHER trial provides, to our knowledge, the first evidence of an independent effect of TILs on OS in patients with ERBB2-positive early breast cancer treated with adjuvant chemotherapy and trastuzumab." (PMID 39946142, 2025). "Perhaps one of the most significant breakthroughs in this area of research is the development of a microfluidic chip-based EV mRNA sensor for the detection of HER2-positive breast cancer via quantitation of EV ERBB2 in the blood." (PMID 40214422, 2025). "Despite these limitations, this study provides valuable insights into the utility of the HER2DX ERBB2 mRNA score in HER2+ advanced breast cancer treated with THP." (PMID 40280938, 2025). "HER2-targeted therapy: Monoclonal antibodies, crucial in HER2-positive breast cancer (early and metastatic), can induce cardiac dysfunction by disrupting HER-2/ERBB2-neuregulin (NRG) signaling, essential for cardiomyocyte growth, repair, and homeostasis." (PMID 40141815, 2025). "Studies have shown that DUSP1 is an important survival protein in breast cancer cells and a key downstream component of ERBB2 signaling." (PMID 40852352, 2025). "ERBB2 encodes the HER2-receptor, and TIMP1 is associated with breast cancer progression and metastasis." (PMID 40905789, 2025). "Out of the presence or absence of three of them, ESR1 (oestrogen receptor), PGR (progesterone receptor), and HER2/ERBB2 (human epidermal growth factor receptor 2/HER2) make a breast cancer triple positive or triple negative." (PMID 40690373, 2025). "ERBB2/HER2 is commonly expressed in many cancers, such as gallbladder cancer, breast cancer, and gastric cancer." (PMID 39830019, 2025).
breast cancer (continued). "This cohort study explores survival among patients with ERBB2-positive metastatic breast cancer with only central nervous system (CNS) metastasis compared with CNS and extracranial metastases." (PMID 39888615, 2025). "The primary outcome was receipt of ERBB2-targeted therapies in the 12 months after diagnosis of ERBB2-positive breast cancer." (PMID 40310643, 2025). "For instance, a phase I trial evaluated a DNA vaccine targeting the intracellular domain of ERBB2 (HER2) in patients with advanced HER2-positive breast cancer." (PMID 40006583, 2025). "EGFR (HER1) and ERBB2 (HER2) are frequently implicated in breast, lung, ovarian, and other malignancies, whereas ERBB3 (HER3) is commonly associated with breast cancer, and ERBB4 (HER4) has been detected in both breast cancer and granulosa cell tumors." (PMID 41230212, 2025). "Amplification of the ERBB2 gene on chromosome 17q12 leads to HER2 overexpression in 15%–25% of breast cancers, driving aggressive tumor behavior and poor clinical outcomes." (PMID 41537091, 2025). "MAPK and PI3K/Akt pathways are interlinked in TGF-β and ErbB2 signaling transduction and have been reported to promote trastuzumab resistance in breast cancer models and primary malignancies (31, –33)." (PMID 39786928, 2025). "Taken together, these findings demonstrate that alpelisib effectively inhibits proliferation and clonogenic potential in erbB2-overexpressing breast cancer cells, underscoring its therapeutic potential in this subtype." (PMID 41347072, 2025). "We also found that DOT1L inhibition suppresses ERBB2 expression in HER2-positive breast cancer cells." (PMID 41299712, 2025). "Together, these data demonstrate correlations and co-localization between ERBB2, SLC9A3R1 and EZR gene expression early during the development of HER2-positive breast cancer." (PMID 40390040, 2025). "This 10-year follow-up analysis of the ShortHER randomized clinical trial evaluates the association of tumor-infiltrating lymphocytes with distant disease-free and overall survival among patients with ERBB2 (formerly HER2)–positive early breast cancer." (PMID 39946142, 2025). "We first evaluated the effect of alpelisib as a single agent on the growth of SK-BR-3 and BT-474 breast cancer cells, both of which overexpress erbB2." (PMID 41347072, 2025). "The cHER2+ breast cancer subtype is characterized by the overexpression of the HER2 oncoprotein based on immunohistochemistry (IHC)/or by ERBB2 gene amplification using in situ hybridization (ISH) techniques." (PMID 41465240, 2025). "Autophagy induction has been shown to be beneficial in breast cancers with amplifications in the receptor tyrosine kinase HER2/ERBB2." (PMID 40754831, 2025). "Our findings in the first-line THP setting further support the prognostic value of HER2DX ERBB2 mRNA score, indicating that ERBB2 mRNA is a robust biomarker across multiple lines of therapy in metastatic HER2+ breast cancer." (PMID 40280938, 2025). "Trastuzumab is among the most commonly used drugs targeting the receptor tyrosine-protein kinase erbB-2 (ErbB2) in breast cancer, but its resistance is inevitable, severely limiting its clinical effectiveness." (PMID 39786928, 2025). "EGFRvIII/IL-13 Rα2 TanCARs have been tested in glioblastoma, while ErbB2/MUC1 TanCARs have been investigated for breast cancer." (PMID 41194129, 2025). "In the Erbb2 breast cancer, a total of 425 differentially expressed genes were identified, of which 159 genes were upregulated and 266 genes were downregulated in Srsf3 KO breast cancer when compared to WT Srsf3 breast cancer." (PMID 40568073, 2025). "In particular, the overexpression of ERBB2 categorizes ERBB2/HER2-positive, a subclass of breast cancer." (PMID 39804726, 2025). "Expression of SULF1 was higher in metastatic breast cancer with ERBB2‐amplification (HER2‐amplification) status." (PMID 38590118, 2025).
breast cancer (continued). "Is the level of tumor-infiltrating lymphocytes (TILs) associated with survival outcomes in patients with ERBB2 (formerly HER2)–positive early breast cancer, and can it guide adjuvant treatment de-escalation?" (PMID 39946142, 2025). "For patients with early ERBB2 (formerly HER2)–positive breast cancer, there is a need to identify biomarkers to guide treatment de-escalation." (PMID 39946142, 2025). "Taken together, these results indicate that NUPR1 positively regulates the expression of ERBB2 and promotes the EGF-ERBB2 pathway-related survival in breast cancer cells." (PMID 39991577, 2025). "Genomic analysis indicates that HER2-low breast cancer exhibits slightly elevated ERBB2 gene expression levels." (PMID 40177129, 2025). "In gastric cancer and breast cancer, patients with high expression of ERBB2 have higher tumor malignancy and poorer prognosis." (PMID 39192657, 2025). "Future studies should aim to evaluate the prevalence of macro-cTn in a larger cohort of ERBB2 + breast cancer patients receiving cardiotoxic cancer therapies, while also assessing long-term health outcomes." (PMID 39953627, 2025). "Consistently, we found conditional Srsf3 KO in mouse mammary glands prevent c-neu (Erbb2) expression and thus, Erbb2 breast cancer induction, providing for the first time the direct in vivo evidence of Srsf3’s oncogenic feature." (PMID 40568073, 2025). "The ERBB2 (Tyrosine kinase receptor-2) gene plays a key regulatory role in the growth and drug resistance of breast cancer." (PMID 40895789, 2025). "This opposite response of Mfsd4a to Srsf3 KO from Erbb2 breast cancer to DEN-induced liver cancer was remarkable by IGV visualization of RNA-seq reads-coverage and easily validated by NanoString analysis." (PMID 40568073, 2025). "Prior research that investigated racial and ethnic disparities in trastuzumab receipt among Medicare beneficiaries with ERBB2-positive breast cancer has shown mixed results." (PMID 40310643, 2025). "Intriguingly, high NUPR1 expression levels also correlate with poor overall survival (despite not reaching statistical significance) and poor relapse-free survival in ERBB2-enriched breast cancer patients." (PMID 39991577, 2025). "In 2017, the FDA approved neratinib for use as extended adjuvant therapy in early-stage ErbB2-positive breast cancer patients who had previously received trastuzumab-based therapy." (PMID 39908697, 2025). "The variant frequency of ERBB2 was third highest in endometrial cancer, seventh in CRC, and eighth in breast cancer." (PMID 40627234, 2025). "HER2 is best known as a key oncogenic driver of breast cancer, in which it is found to be overexpressed in about 20% of cases, either because of ERBB2 amplification or activating somatic mutations." (PMID 40767528, 2025). "We discovered Srsf3 plays an oncogenic role in breast cancer and Srsf3 knockout (KO) in mammary glands delays the development of breast cancer in an Erbb2 mouse model." (PMID 40568073, 2025). "In a breast cancer dataset comprising 11 samples, only one patient received trastuzumab treatment and harbored ERBB2 i14e isoform." (PMID 39948369, 2025). "Estrogen receptor (ER), progesterone receptor (PGR), and erb-b2 receptor tyrosine kinase 2 (ERBB2) are three important receptors that are commonly utilized to categorize breast cancers." (PMID 40723371, 2025). "The bioinformatics study revealed a correlation between PARP2 and BRCA1/2 and ERBB2 in the basal subgroup of breast cancer patients." (PMID 40141415, 2025). "Of the 136 patients recruited into the EMBRACE-MRI study, 12 ERBB2 + breast cancer patients were included in this pilot study." (PMID 39953627, 2025).
breast cancer (continued). "This study was designed to test the effect of alpelisib on erbB2-overexpressing breast cancer and the potential synergetic effect of combining metformin with alpelisib therapeutic regimen." (PMID 41347072, 2025). "Targeted inhibition of ERBB2 expression can suppress the growth and invasion of breast cancer cells." (PMID 41305721, 2025). "Studies have shown that ERBB2 relies on HIF-1 to promote breast cancer growth in vivo, enhancing the adaptability of tumor cells to hypoxic environments through HIF-1-mediated signaling pathways, thereby generating oxygen resistance." (PMID 40895789, 2025). "Despite well-documented racial and ethnic disparities in breast cancer treatment, our findings show a narrowing of disparities in the receipt of ERBB2-targeted therapies over time among Medicare beneficiaries with ERBB2-positive breast cancer." (PMID 40310643, 2025). "The objectives of this study were to examine the receipt and changes in use of ERBB2-targeted therapies by race and ethnicity over time among older adults with localized or regional stage ERBB2-positive breast cancer." (PMID 40310643, 2025). "Srsf3 KO was found to reduce Srsf1 protein expression both from the Erbb2 breast cancer and DEN-induced liver cancer." (PMID 40568073, 2025). "Among Medicare beneficiaries diagnosed with ERBB2 (formerly HER2 or HER2/neu)–positive breast cancer between 2010 and 2019, are racial and ethnic disparities associated with receipt of ERBB2-targeted therapies, and do these trends change over time?" (PMID 40310643, 2025). "In conclusion, the results from this study demonstrate that alpelisib offers potent anti-tumor activity in erbB2/HER2-overexpressing breast cancer, which can be significantly enhanced by combining it with metformin." (PMID 41347072, 2025). "And TOM1L1 was able to promote ERBB2-induced breast cancer cell invasion by driving membrane delivery of membrane-type 1 matrix metalloprotease (MT1-MMP)." (PMID 40303916, 2025). "Here, the MMTV-neu allele expresses WT ERBB2 protein in mammary epithelium, leading to ERBB2, also known as HER2+ mammary tumor in female mice." (PMID 41387465, 2025). "Molecularly, the detection of ERBB2 amplification in 57% (first PCR) and 72% (nested PCR) of patients, with frequencies of 80% and 17% in daughters and 79% and 20% in sisters, respectively, underscores the hereditary component of ERBB2-driven breast cancer." (PMID 41403731, 2025). "Trastuzumab is the first monoclonal antibody to be approved for a solid carcinoma, which targets the extracellular domain of the human epidermal growth factor receptor 2 (HER2/ErbB2) in breast cancer and other solid tumors." (PMID 40584631, 2025). "Beyond breast cancer, ERBB2 amplification and HER2 overexpression are observed across other various tumor types such as gastric, bladder, colorectal, bile duct, and non-small cell lung cancers." (PMID 40098704, 2025). "Lapatinib, a dual tyrosine kinase inhibitor used for ErbB2-positive breast cancer, inhibits CIP2A, resulting in the inactivation of Akt signaling and increased apoptosis in cancer cells." (PMID 41155727, 2025). "In MCF-7 cells, a representative luminal A breast cancer cell line with low ErbB2 expression, the G1/S transition is normally regulated by the cyclin D1/CDK4 complex via Hsp90." (PMID 41161384, 2025). "We also demonstrate that DOT1L inhibition suppresses proliferation of HER2-positive breast cancer cells, at least in part, by suppressing ERBB2 expression." (PMID 41299712, 2025). "Erbin has been reported to promote interactions between HER2 and HSP90, and HSP90 is also required to maintain activated ErbB2 within protruding membrane domains on the surface of breast cancer cells." (PMID 40390040, 2025). "Fifth, our analysis focused on the receipt of clinician-administered therapies indicated to treat ERBB2-positive breast cancer; therefore, future studies are needed to understand disparities and trends in the use of orally administered medications." (PMID 40310643, 2025).